NLRP3 (NLR family pyrin domain containing 3)
Diseases named in the same sentence as NLRP3 in open-access papers (continued):
Sharing a sentence is not in itself a finding about the gene and the disease.
inflammatory bowel disease (continued). "In conclusion, CAC can be prevented by CAPE-induced NLRP3 inflammasome inhibition, highlighting CAPE as a potential candidate for reducing the risk of CAC in patients with inflammatory bowel disease." (PMID 32435622, 2020). "Nucleotide-binding oligomerization domain leucine rich repeat and pyrin domain-containing protein 3 (NLRP3) inflammasome is pivotal in maintaining intestinal homeostasis and sustaining enteric immune responses in the setting of inflammatory bowel diseases." (PMID 30559669, 2018). "It is logical to assume that a major pro-inflammatory mechanism, i.e., the NLRP3 inflammasome would play a prominent role in the pathogenesis of the Inflammatory Bowel Disease (IBD) in humans." (PMID 30455704, 2018). "Inhibition of NLRP3 inflammasome activation provides protective effects in renal fibrosis and inflammatory bowel disease." (PMID 29070054, 2017). "Similar mechanisms have been documented in inflammatory bowel disease and respiratory virus infections, where an hyperactivation of the NLRP3 inflammasome was correlated with increased XO expression and activity, and support the inhibition of XO as a potential therapeutic target." (PMID 41398526, 2025). "Besides IM-associated liver injury, the mechanism of GBP5 in activating the NLRP3 inflammasome plays a key role in the pathogenesis of inflammatory bowel diseases and arthritis." (PMID 40075517, 2025). "Moreover, DSS, which is used in mouse models of inflammatory bowel disease, augments NLRP3 inflammasome activation through the K+ channel KCa3.1." (PMID 40307577, 2025). "The pyrin domain-containing protein 3 (NLRP3) inflammasome may be a potential target for the treatment of inflammatory bowel disease (IBD), and inhibiting the activation of the NLRP3 inflammasome is of great significance for the treatment of IBD." (PMID 40871494, 2025). "Furthermore, NLRP3-driven inflammation appears to play a role not only in asthma but also in inflammatory bowel disease and juvenile idiopathic arthritis, indicating a wider relevance for therapies that target the inflammasome pathway." (PMID 41318536, 2025). "Patients with inflammatory bowel disease, which involves an autoimmunity-associated PTPN22 variant, exhibit increased IL-1β levels, underscoring the role of Y861 phosphorylation in regulating NLRP3 and preventing aberrant inflammasome activation." (PMID 40307577, 2025). "Consequently, a plethora of NLRP3 inhibitors have been deployed as therapeutic agents for inflammatory bowel disease management." (PMID 40640149, 2025). "However, the overexpression of the NLRP3 inflammasome often results in severe inflammatory diseases, such as inflammatory bowel diseases (Crohn’s disease and ulcerative colitis) or intestinal invasive bacterial infections." (PMID 39519712, 2024). "Notably, NF-κB signalling reportedly regulates the interaction of NEK7 and NLRP3, thereby modulating pyroptosis in inflammatory bowel disease." (PMID 39334337, 2024). "Additionally, a decrease in Alistipes (A. finegoldii) and Odoribacter (O. splanchnicus), which have protective roles against inflammatory bowel disease, was noted in the faecal flora of Nlrp3−/− mice." (PMID 39605303, 2024). "Extensive research has been performed on NLRP3, which may have a role in several disorders, including Inflammatory bowel disease (IBD), Alzheimer’s disease, obesity, atherosclerosis, and endotoxin shock." (PMID 36713830, 2023). "Therefore, several autoimmune diseases, including SLE, psoriasis, multiple sclerosis (MS), rheumatoid arthritis (RA) or inflammatory bowel diseases (IBD), can be associated with NLRP3 overactivity." (PMID 36293012, 2022). "With the deepening of research work, NLRP3 may become a therapeutic target for intervening intestinal diseases such as inflammatory bowel disease and intestinal infection, but more clinical studies are needed before practical application." (PMID 36497018, 2022).
inflammatory bowel disease (continued). "Besides, in inflammatory bowel disease, levels of IL-1β in MLNs increase significantly, and inhibition of NLRP3/IL-1β signal axis is thought to improve the symptoms of SAE." (PMID 35111693, 2021). "Activation of the NLRP3 inflammasome induces the maturation and production of the proinflammatory cytokines interleukin 1β (IL-1β) and IL-18, which further induce inflammation in inflammatory bowel diseases." (PMID 34043726, 2021). "Functional enrichment analysis revealed enriched inflammatory bowel disease (adjusted P value = 0.016), NLRP3 inflammasome (adjusted P value = 0.045), ABIN2-NFKB1-MAP3K8 complex (adjusted P value = 0.0498), and prion disease pathways (adjusted P value = 0.0499)." (PMID 33542415, 2021). "Thus, our results demonstrate the ability of C646 to suppress the NLRP3 inflammasome activity and its potential application in the treatment of inflammatory bowel disease." (PMID 34322027, 2021). "With the inappropriate release of proinflammatory cytokines, the NLRP3 inflammasome is involved in various inflammatory diseases, such as atherosclerosis, type 2 diabetes, Alzheimer’s disease, gout, rheumatoid arthritis, and inflammatory bowel disease." (PMID 33364979, 2020). "A later study showed that NEK7 may also be involved in inflammatory bowel disease mediated by NLRP3 inflammasome activation, the mechanism of which has been described in the previous section." (PMID 33364979, 2020). "Indeed, NLRP3 is activated in patients with inflammatory bowel disease and overexpression and constitutive activation of NLRP3 inflammasome contribute to the progression of head and neck squamous cell carcinoma, lung cancer, and colorectal cancer." (PMID 32435622, 2020). "The NLRP3 inflammasome is involved the progression of asthma and inflammatory bowel diseases." (PMID 31312615, 2019). "Several studies have been performed on the association of the genetic alterations in genes encoding NLRP3 and CARD8 with the complex diseases with inflammatory background, like inflammatory bowel disease, cardiovascular diseases, rheumatoid arthritis, and type 1 diabetes." (PMID 25788762, 2015). "Furthermore, recent evidence suggests that the NLRP3 inflammasome and its maturation of IL-18 downregulates the IL-22 binding protein, an inhibitor of IL-22, which promotes cell repair in inflammatory bowel diseases." (PMID 24312491, 2013). "In PSC patients with concurrent inflammatory bowel disease (IBD), gut microbiome-derived OMVs travel to the liver and trigger NLRP3 inflammasome activation in hepatic cells, exacerbating liver inflammation and fibrosis." (PMID 40862753, 2025). "This study sought to explore the effect of electroacupuncture (EA) intervention at Zusanli (ST36) acupoint on modulating the NLRP3 inflammasome pathway for treating inflammatory bowel disease (IBD)." (PMID 39119947, 2024). "Aberrant activation of the NLRP3 inflammasome promotes the pathogenesis of inflammatory diseases, including chronic kidney disease, type II diabetes, atherosclerosis, neurodegenerative diseases, inflammatory bowel disease, gout, rheumatoid arthritis, cancers, and some infectious diseases." (PMID 35967819, 2022). "It has been found that NLRP3 and its mediated production of IL-1β could promote the development of inflammatory bowel disease, which, eventually, might develop into gastrointestinal malignancies, thus suggesting that pyroptosis actions an essential part in this process." (PMID 35571569, 2022). "NLRP3 inflammasome has emerged as a crucial regulator of inflammatory bowel disease (IBD) characterized by a chronic inflammatory disease of the gastrointestinal tract." (PMID 34093533, 2021). "Moreover, NLRP3 activation may be involved in patients suffering from inflammatory bowel disease (IBD)." (PMID 32764281, 2020). "Based on the transcriptomic results, we constructed a rat model of inflammatory bowel disease (IBD) with LPS and investigated the effects of α-MG on NLRP3 inflammasomes." (PMID 31666566, 2019).
inflammatory bowel disease (continued). "Moreover, special attention has been paid to the pharmacological modulation of NLRP3 inflammasome, emphasizing the concept that this multiprotein complex could represent a suitable target for the management of inflammatory bowel diseases." (PMID 28179906, 2017). "Taken together, our results demonstrated that inhibition of the protease activity of MALT1 might be a viable strategy to treat inflammatory bowel disease and the NLRP3 inflammasome and NF-κB activation are critical components in MALT1 signaling cascades in this disease model." (PMID 27105502, 2016). "For instance, studies have shown that miR-539-5p from MSC-Exos can target NLRP3 in intestinal epithelial cells, modulating the process of pyroptosis in a mouse model of inflammatory bowel disease (IBD), thereby alleviating the progression of IBD." (PMID 41425572, 2025). "Overactivation of NLRP3 has been implicated in several pediatric inflammatory disorders, including asthma, juvenile idiopathic arthritis (JIA), and inflammatory bowel disease (IBD), all of which share a common pathway involving NLRP3 activation and cytokine-driven inflammation." (PMID 41318536, 2025). "For instance, the 3,4-methylenedioxy-β-nitrostyrene (MNS) that has been demonstrated to treat inflammasome activation-induced inflammatory bowel disease (IBD), prevents NLRP3-mediated ASC speck formation and oligomerization and inhibits NLRP3 ATPase activity by binding to NLRP3 LRR and NLRP3 NACTH." (PMID 38644450, 2024). "NLRP3 is associated with the development of such autoimmune conditions as rheumatoid arthritis (RA), systemic lupus erythematosus (SLE), systemic sclerosis (SSc), and inflammatory bowel disease (IBD)." (PMID 40012912, 2024). "In conclusion, we systematically summarized the landscape of pyroptosis in inflammatory bowel disease and identified AIM2, CASP1, CASP5, GSDMD, and NLRP3 as hub genes." (PMID 37740137, 2023). "LCN2 also plays a role in the pathophysiology of inflammatory bowel disease (IBD) and upregulates the NLRP3 inflammasome via NF‐κB activation." (PMID 37353794, 2023). "ADP released from injured colonic tissue can also activate the NLRP3 inflammasome through P2Y1 receptor-mediated calcium signaling, thereby regulating inflammatory bowel disease." (PMID 35883561, 2022). "However, in vivo studies investigating the role of the NLRP3 inflammasome in inflammatory bowel disease (IBD) report contrasting results, leaving it unclear if the NLRP3 inflammasome augments or attenuates intestinal inflammation." (PMID 35911682, 2022). "For example, the involvement of NLRP3 inflammasome dysregulation in Kawasaki disease (KD) has raised great interest, like its involvement in juvenile SLE (JSLE), inflammatory bowel disease (IBD) and systemic juvenile idiopathic arthritis (sJIA)." (PMID 34198614, 2021). "However, excessive inflammation via NLRP3 activation results in serious diseases such as arthritis, asthma, inflammatory bowel disease (IBD), Parkinson's disease, Alzheimer's disease, and sepsis 15-22." (PMID 32410829, 2020). "Indeed, an overactivation of NLRP3 inflammasome signaling has been observed in the brain and blood of patients with neurological disorders, adipose tissue macrophages from obese and diabetic patients, as well as patients with rheumatoid arthritis (RA) and inflammatory bowel diseases (IBDs)." (PMID 31200447, 2019). "NLRP3 inflammasome is a novel therapeutic target for inflammatory bowel disease (IBD)." (PMID 28938606, 2017). "Moreover, the increased IL-1β and ASC expression can be detected in the colon of patients with inflammatory bowel diseases (IBDs), while systemic lupus erythematosus (SLE) patients exhibit an increased level of NLRP3 proteins in macrophages and tissues." (PMID 35883561, 2022).
inflammatory bowel disease (continued). "However, aberrant activation of NLRP3 inflammasome has been reported to promote the development of several human diseases, including gout, type 2 diabetes (T2D), inflammatory bowel disease (IBD), atherosclerosis, neurodegenerative diseases and others." (PMID 35250572, 2022). "Recent studies have shown that NLRP3 inflammasome plays a pivotal role in various diseases, such as CRS, asthma, obstructive pulmonary disease, inflammatory bowel disease, metabolic disorders, multiple sclerosis, and other auto-immune and auto-inflammatory diseases." (PMID 35256715, 2022). "The NLRP3 inflammasome has consistently been shown to participate in the pathogenesis of many autoimmune disorders, including MS (multiple sclerosis), EAE (experimental autoimmune encephalomyelitis), IBD (inflammatory bowel disease) and T1DM." (PMID 32973739, 2020). "Moreover, activation of the NLRP3 inflammasome also plays an important role in the nonspecific inflammation of inflammatory bowel disease (IBD)." (PMID 32148650, 2020). "According to research, the excitation of NLRP3 inflammasome played a crucial function in nonspecific inflammation of inflammatory bowel disease (IBD)." (PMID 35682929, 2022). "An important role for NLRP3 inflammasome and its dysregulation has been defined not only in microbial host-response but also in metabolic dysfunction, inflammatory bowel disease (IBD), and colorectal cancer." (PMID 29868004, 2018).
rheumatoid arthritis (178 papers, 2014 to 2026). A chronic, systemic autoimmune disorder characterized by inflammation in the synovial membranes and articular surfaces. "The NLRP3, inflammasome is several implicated in multiple autoimmune diseases, including systemic lupus erythematosus, SS and rheumatoid arthritis." (PMID 41255601, 2025). "Elevated levels of NLRP3 have been observed in the bronchoalveolar lavage fluid (BALF) of rheumatoid arthritis-associated interstitial lung disease (RA-ILD) patients." (PMID 40391214, 2025). "Abnormal activation of NLRP3‐mediated pyroptosis has been linked to the progression of inflammatory bone loss disorders such as osteoporosis, periprosthetic osteolysis, rheumatoid arthritis, psoriatic arthritis, and ankylosing spondylitis." (PMID 40492417, 2025). "Epigenetic licensing of the NLRP3 inflammasome is strongly associated with the pathogenesis of rheumatoid arthritis." (PMID 40307577, 2025). "The abnormal activation of NLRP3 is strongly linked to several chronic inflammatory diseases, such as metabolic syndrome, rheumatoid arthritis, and pancreatic cancer." (PMID 40535567, 2025). "The NLRP3 inflammasome plays a crucial role in both the innate and adaptive immune systems and is linked to various autoimmune diseases, including rheumatoid arthritis and systemic lupus erythematosus (SLE)." (PMID 38433222, 2024). "There is growing evidence that the NLRP3 inflammasome plays a pathogenic role in chronic inflammatory diseases that exhibit circadian rhythmicity, such as rheumatoid arthritis, hepatitis, and asthma." (PMID 39686706, 2024). "Vaccine adjuvants enhance vaccine immunogenicity by activating the NLRP3 inflammasome, a crucial immune system component linked to autoimmune diseases like ankylosing spondylitis, rheumatoid arthritis, systemic lupus erythematosus, SS, and systemic sclerosis." (PMID 39421077, 2024). "The purpose of this study is to examine the associations of NLRP3 gene polymorphisms with rheumatoid arthritis (RA) and primary Sjogren’s syndrome (SS) patients." (PMID 36673016, 2023). "The finding also indicates that A20 deficiency in macrophages significantly enhances NLRP3 inflammasome-mediated caspase-1 activation and IL-1 β secretion, which contributes to the pathology of rheumatoid arthritis in vivo." (PMID 35794098, 2022). "Deficiency of NLRP3 or caspase-1/-11 in A20 knockout mice protected against the inflammatory symptoms of rheumatoid arthritis, which showed that A20 negatively regulated NLRP3 inflammasome activity in rheumatoid arthritis." (PMID 36387275, 2022). "Mitochondria are also an important source of intracellular reactive oxygen species, and facilitate the activation of the NLRP3 inflammasome, which produces cytokines linked to disease symptoms in rheumatoid arthritis." (PMID 33995417, 2021). "Here we shall focus solely on the mitochondria-linked mechanisms of regulation, and the relevance of NLRP3 activity to rheumatoid arthritis." (PMID 33995417, 2021). "NLRP3/CARD8−/− genetic mutations are common in patients with rheumatoid arthritis and are associated with an increase in incidence and severity of rheumatoid arthritis symptoms." (PMID 33534121, 2021). "Excessive and persistent activation of the NLRP3 inflammasome leads to loss of the control of IL-1β processing and contributes to several immune diseases, such as rheumatoid arthritis, systemic lupus erythematosus, gout and colitis." (PMID 33542692, 2020). "IL-1β generation is mainly mediated by the NLRP3 inflammasome, and deletion of Nlrp3, caspase-1 and the IL-1 receptor markedly protects against rheumatoid-arthritis-associated inflammation." (PMID 29743895, 2018). "Genetic variations in NLRP3-inflammasome components have been reported to influence rheumatoid arthritis (RA) susceptibility and severity." (PMID 26385789, 2015).